BRCA1 (BRCA1 DNA repair associated)
Diseases named in the same sentence as BRCA1 in open-access papers (continued):
Sharing a sentence is not in itself a finding about the gene and the disease.
ovarian carcinoma (continued). "The role of BRCA1 in DNA damage response was most prominent in LoVo-92/cOHP and LoVo-Li/4OHP, but the ovarian cancer cell lines also showed altered expression of genes in this pathway." (PMID 31344863, 2019). "Germline mutations in BRCA1 and BRCA2 are associated with greatly increased frequency of breast and ovarian cancers and telomere shortening was associated with genetic anticipation in hereditary breast cancer." (PMID 30995915, 2019). "Poly (ADP-Ribose) polymerase (PARP) inhibitors have been also used in advanced ovarian cancer patients with BRCA2 and BRCA1 mutations." (PMID 31810474, 2019). "A germline gene mutation in BRCA1 or BRCA2 results in a significantly elevated lifetime risk of developing breast and ovarian cancer estimated at up to 7 and 25 times, respectively, compared to average risk population." (PMID 31200461, 2019). "BRCA1- and BRCA2-deficient ovarian cancers in an unselected cohort of ovarian cancer patients were also shown to have increased PD-L1 and PD-1 expression compared to BRCA-proficient ovarian cancers." (PMID 31022191, 2019). "In relapsed platinum-sensitive disease, BRCA1/2-mutant ovarian cancer, the olaparib durvalumab combination demonstrated an ORR of 63%, which is also compatible with the PARP inhibitor monotherapy activity in this setting." (PMID 31109041, 2019). "In the phase II study among 32 patients with germline BRCA1/2 mutant platinum-sensitive ovarian cancer, disease control rate at 12 weeks and ORR were 81% and 63%, respectively." (PMID 31374917, 2019). "Increased NF-κB signaling and elevated ISG15 expression were recently observed also in BRCA1 mutants of fallopian tube epithelial cells and in ovarian cancer cells." (PMID 31903170, 2019). "In conclusion, this first real-life survey can offer a picture of the current Italian situation for the BRCA1/2 test in ovarian cancer." (PMID 31600986, 2019). "Current evidence suggests that specific inherited mutations of BRCA1 and BRCA2 are attributed to an enhanced risk of female BC and ovarian cancer (OV)." (PMID 30975222, 2019). "They reported on the prevalence of BRCA1 and / or BRCA2 mutations among breast or/ and ovarian cancer patients." (PMID 30898109, 2019). "This indicates that BRCA1-mediated DNA repair is important for maintaining a normal differentiation state and suppressing the development of breast- and ovarian cancer." (PMID 31213009, 2019). "Beyond prostate cancer, germline BRCA1 and BRCA2 mutations are known to increase the risk of other tumor types including breast and ovarian cancers." (PMID 30871108, 2019). "Specific inherited mutations in BRCA1 and BRCA2 increase the risk of female breast and ovarian cancers, and they have been associated with increased risks of several additional types of cancer." (PMID 31865918, 2019). "Effect of genetic and epigenetic alterations in the BRCA1 gene is attributed in many malignancies including breast and ovarian cancers." (PMID 31653147, 2019). "Mutation analysis of BRCA1 and BRCA2 genes was performed in 44 women diagnosed with primary or recurrent high-grade ovarian cancer from three different samples: blood, cytological sample (ascites, pleural effusion and enlarged lymph nodes) and tumor tissue." (PMID 30940100, 2019). "Our findings demonstrated that BRCA1 mediated ovarian cancer characteristics including drug resistance and stemness of EOCSCs by modulating autophagy." (PMID 30636383, 2019).
ovarian carcinoma (continued). "Of these CNVs, BRCA1 (exon 4-13 absence, exon 12-18 absence) and ATM (exon 57-63 absence) were potentially associated with susceptibility to ovarian carcinoma." (PMID 31257224, 2019). "Germline mutations in these genes are associated with approximately 25% of the familial cases of breast and ovarian cancer and a significant proportion of sporadic cancers show BRCA1 and BRCA2 gene inactivation." (PMID 31273933, 2019). "BRCA1 and BRCA2 are breast and ovarian cancer susceptibility genes with a strong hereditary component." (PMID 31387612, 2019). "We analyzed the relationship between resistant levels and BRCA1 levels in ovarian cancer tissue samples." (PMID 30636383, 2019). "In particular, a case-control study conducted in France found significantly decreased BRCA1 methylation in peripheral blood cells of 51 sporadic ovarian cancer cases compared with 349 healthy female controls." (PMID 31261650, 2019). "In individuals with BRCA1 and BRCA2 mutations, the risk of breast and ovarian carcinoma development is very high." (PMID 30713775, 2019). "Germline mutations in BRCA1 and BRCA2 are known risk factors for ovarian cancer, particularly the HGSC subtype." (PMID 31366178, 2019). "Corresponding mutations in the BRCA1, BRCA2, PALB2 genes are detected in a fraction of sporadic breast and ovarian cancer." (PMID 35582724, 2019). "DNA microarray analysis in morphologically normal ovarian surface epithelial cells from women with germline mutations of BRCA1 or BRCA2 and ovarian cancer cells identified genes that were up-regulated by DHT treatment." (PMID 30791431, 2019). "Three studies well defined in ovarian cancer includes: Methylation of either BRCA1, GSTP1, or MGMT significantly correlates with improved response to chemotherapy (p = 0.013)." (PMID 31608277, 2019). "Twelve families in our curated dataset reported family or personal history of breast or ovarian cancer, five of which had germline BRCA1/2 detected, and three probands had positive BRCA2 germline mutations." (PMID 31703574, 2019). "Mutations in the BRCA1 and BRCA2 genes predispose carriers to a higher risk of breast and ovarian cancer." (PMID 31671674, 2019). "This is perhaps due to the reduced expression of BRCA1 in circPLEKHM3 knockdown cells that increases the resistance of Taxol for treating ovarian cancer." (PMID 31623606, 2019). "In the present study, we have assessed the aberrant promoter hypermethylation status of RASSF1a and BRCA1 in the cell-free circulating DNA (cfc DNA) of ovarian carcinoma patients using methylation-specific PCR." (PMID 31653147, 2019). "Taken together these results suggest that E2F4 is an activator of BRCA1 transcription in ovarian cancer cells." (PMID 31604914, 2019). "The interaction of BARD1 to BRCA1 is mediated by their respective RING domains leading to the proposal that BARD1 is a candidate breast and ovarian cancer predisposing gene." (PMID 31803232, 2019). "BRCA1: A functional SNP, rs8176318, located in the 3′UTR of BRCA1, has been reported to predict breast (including TNBC) and ovarian cancer risk in a population of Irish women." (PMID 30897768, 2019). "Individuals carrying pathogenic BRCA1 or BRCA2 mutations have an increased lifetime risk of breast and/or ovarian cancer." (PMID 30980249, 2019). "The search for markers of ovarian cancer development was carried on in the further part of the study by an analysis of the polymorphisms of HR genes (RAD51 and BRCA1)." (PMID 30712190, 2019). "BRCA1, CDKN1B, PPP1CC, SKP2, and URI1 were clustered in subnetwork 8 and categorized as shared proteins in PCOS and ovarian cancer, hence suggesting an association between the two." (PMID 31216618, 2019). "Among the 7 patients with both breast and ovarian carcinomas, only 3 patients (42.8%) exhibited BRCA1/2 positivity." (PMID 30713775, 2019).
ovarian carcinoma (continued). "Given that the SNP protective effect is for ovarian cancer, we also determined UNG mRNA expression in tissues of 17 prophylactic oophorectomies from BRCA1 and BRCA2 mutation carriers." (PMID 30747491, 2019). "Previous studies indicated that deficiencies in DNA repair pathways, such as BRCA1 and BRCA2 mutations, can increase PARPi activity in breast and ovarian cancer." (PMID 30736840, 2019). "In a recent study, we examined WBC BRCA1 promoter methylation status among 1688 healthy controls and 925 patients with ovarian cancer." (PMID 31225507, 2019). "Women with BRCA1 and BRCA2 mutations have a higher risk of ovarian cancer at the age of 70 years at 39-46% and 10-27%, respectively." (PMID 30362670, 2019). "BRCA1 BRCT domain mutations result in loss of tumor suppressor activity and are commonly found in patients with hereditary forms of breast and ovarian cancer." (PMID 31827092, 2019). "As for studies examining BRCA1 promoter methylation with respect to breast and ovarian cancer, blood samples in general were collected from patients already diagnosed with their cancer." (PMID 31225507, 2019). "There were 3 (2.2%) variant-positive females who had more than one cancer, all of whom had both breast and ovarian cancers: one with BRCA1 c.68_69delAG and two with BRCA2 c.5946delT." (PMID 31892343, 2019). "MiR-9 mediates the downregulation of BRCA1, impedes DNA damage repair in ovarian cancer and improves chemotherapeutic efficacy by increasing the sensitivity of cancer cells to DNA damage." (PMID 31001476, 2019). "The differential expression of BRCA1 in EOCSCs was evaluated, as well as the relationship between autophagy and the resistance of ovarian cancer to cisplatin‐based chemotherapy." (PMID 30636383, 2019). "This is indeed the case as demonstrated by a recent clinical trial in which patients with BRCA1/2 mutated, PARP inhibitor‐resistant ovarian cancers showed a robust response to platinum‐based therapies." (PMID 31273933, 2019). "Consistent with the RNA-seq analysis, ZC3H18 depletion profoundly decreased BRCA1 mRNA and protein levels in multiple ovarian cancer cell lines and in xenografted OVCAR-8 cells." (PMID 31604914, 2019). "More recent studies in populations from different countries showed a wider range of frequency of pathogenic variants in BRCA1 or BRCA2 depending on the study, with the highest frequencies found in Asian populations reaching 27% of ovarian cancer patients." (PMID 30606148, 2019). "Hypermethylation of CpG islands of OPCML, DCR1, RASSF1A, BRCA1, and many other genes have been detected in early stage of ovarian cancer." (PMID 31366178, 2019). "In the same study, we examined the BRCA1 methylation status in normal as well as ovarian cancer tissue in a subgroup of patients." (PMID 31225507, 2019). "In contrast, our studies in multiple ovarian cancer cell lines found that E2F1 represses BRCA1 expression, and that this repression requires the DNA methyltransferase DNMT1 and is correlated with CpG hypermethylation of the BRCA1 promoter." (PMID 31604914, 2019). "Here we show that quantitative BRCA1 methylation analysis provides new insight into PARPi response in preclinical models and ovarian cancer patients." (PMID 30266954, 2018). "As a result of carrying mutations in BRCA1 and BRCA2 women carry a 40% lifetime risk of epithelial ovarian cancer." (PMID 29925418, 2018). "Signature 3 (BRCA signature), associated with inactivating BRCA1 or BRCA2 mutations in breast and pancreatic cancers and prevalent in ovarian cancer, is present in 27/39 samples." (PMID 30382883, 2018). "Mechanisms contributing to HRD in sporadic EOC include BRCA1 hypermethylation, occurring in 5–31% of sporadic ovarian cancer." (PMID 29925418, 2018).
ovarian carcinoma (continued). "BRCA1 promoter methylation appears to be more relevant for sporadic than for hereditary breast and ovarian cancers." (PMID 30453575, 2018). "The current standard RRSO at age 35–40(BRCA1) or 40–45 (BRCA2) is highly effective in reducing ovarian cancer incidence." (PMID 30340058, 2018). "PARP inhibitors have become the paradigm of drug‐mediated synthetic lethality in HRR‐deficient tumors and have shown clinical efficacy in patients with BRCA1/2‐related breast and ovarian cancers." (PMID 30377213, 2018). "This technology became meanwhile standard in somatic BRCA1/2 testing in ovarian cancer and was also the choice of methodology in our study." (PMID 29453630, 2018). "There were 5712 women tested for a BRCA1 and BRCA2 mutation at the HCP between 2001 and 2014, 887 of which had previously received a diagnosis of ovarian cancer." (PMID 29506471, 2018). "BRCA1 and BRCA2 germline mutations are the most frequently responsible for hereditary breast and ovarian cancer." (PMID 29882921, 2018). "Recently, the landscape of genetic risk evaluation for breast/ovarian cancer expanded due to the introduction of the NGS technology, which has greatly simplified the search for genetic alterations in targets other than BRCA1/2." (PMID 29271107, 2018). "Here, we discuss some key mutations in BRCA1 and BRCA2 that have strong correlation with breast and ovarian cancer and their functional consequences." (PMID 29459887, 2018). "Mutations in BRCA1 and BRCA2 (BRCA1/2) genes are associated with an increased risk of breast and ovarian cancers in women." (PMID 29433453, 2018). "Since the frequency of BRCA-carriers was significantly lower, including cases with family history of breast or ovarian cancer, than in other regions, the study based on sequencing of whole BRCA1 and BRCA2 should be performed." (PMID 29492181, 2018). "Germline sequence and large rearrangements for BRCA1/2 were tested in 398 consecutive epithelial ovarian cancer (EOC) patients." (PMID 30103829, 2018). "Currently, there is consensus that the BRCA1 and BRCA2 mutations are responsible for an average of only 16% of the risk for familial breast and ovarian cancers." (PMID 30135399, 2018). "Germline mutations in BRCA1 and BRCA2 (BRCA1/2) are associated with increased risk of breast and ovarian cancer." (PMID 29861850, 2018). "A turn-on sensing platform in choline dhp was built for the detection of the BRCA1 gene, which is related to familial breast and ovarian cancers." (PMID 30404141, 2018). "Approximately 10–15% of ovarian carcinomas (OC) are attributed to inherited susceptibility, the majority of which are due to mutations in BRCA1 or BRCA2 (BRCA1/2)." (PMID 29298688, 2018). "The aim of this study was to describe BRCA1 and BRCA2 gene variants in Mexican patients with ovarian cancer." (PMID 29997359, 2018). "Since BRCA1 and BRCA2 mutated cells lack HR pathways, such inhibitors improve the effectiveness of chemotherapy in breast and ovarian cancer treatment." (PMID 29882812, 2018). "Hereditary breast and ovarian cancer syndrome, which is related to mutations in the BRCA1 and BRCA2 genes, is an important cause of ovarian carcinoma." (PMID 30517521, 2018). "The first observations of a double mutation in the BRCA1 and BRCA2 genes was found in 1997 in a casistica of patients of Ashkenazi origin affected by breast and ovarian cancer carrying both the 185delAG in the BRCA1 and the 6174delT BRCA2 gene mutations." (PMID 29346284, 2018). "High BRCA1 expression in drug‐resistant ovarian cancer cells has been shown to enhance cellular DNA repair capability, making cells less susceptible to chemotherapeutic drugs and leading to drug resistance (Zhou, Smith, & Liu, 2003)." (PMID 29797793, 2018). "Germline loss-of-function mutations in BRCA1 or BRCA2 have been implicated in increased risk of breast and ovarian cancers." (PMID 30463359, 2018).
ovarian carcinoma (continued). "Based on these results, we launched INST 1419: A phase I/II study of the combination of olaparib and tremelimumab in BRCA1 and BRCA2 mutation carriers with recurrent ovarian cancer (NCT02571725)." (PMID 30400835, 2018). "Constitutional loss-of-function pathogenic variants in the tumor suppressor genes BRCA1 and BRCA2 are widely associated with an elevated risk of ovarian cancer (OC)." (PMID 30441849, 2018). "We have described the genetic variants in BRCA1 and BRCA2 of tumors from Northeast Mexican patients with sporadic ovarian cancers." (PMID 29997359, 2018). "Martin and Ouchi, 2005 have shown that BRCA1 interacts with X-linked inhibitor of apoptosis protein (XIAP) in an ovarian carcinoma cell line SNU-251 and that the BRCA1-XIAP complex is disrupted by UV-induced phosphorylation of BRCA1." (PMID 30323899, 2018). "The aim of this study was to evaluate the prevalence and spectrum of 13 BRCA1 and BRCA2 causative founder variants in unselected patients diagnosed with ovarian cancer from Region of Podkarpacie." (PMID 29492181, 2018). "For example, BRCA1 methylation has been revealed to predict significantly higher response rates to cisplatin treatment in breast and ovarian cancer patients, which is also traditionally used as the first-line agent in bladder cancer disease management." (PMID 29445424, 2018). "BRCA1 mutations account for about 16.3% of ovarian cancers, and BRCA2 mutations account for 6% of ovarian cancers." (PMID 30551670, 2018). "BRCA1 and BRCA2 mutations are detected in around 5–9% and 3–4% of spontaneous ovarian cancer, respectively." (PMID 30042330, 2018). "The cumulative estimates of ovarian cancer in Caucasians ranged from 16-68% and 11-27% for BRCA1 and BRCA2 carriers respectively, which are in line with our findings that BRCA2 carriers tend to have a lower risk of ovarian cancer." (PMID 29861850, 2018). "Surveillance is especially critical for women with BRCA1 and BRCA2 mutations due to the increased risk of ovarian cancer." (PMID 29466291, 2018). "we used our retrospective data based on thousands of ovarian cancer women sequenced for BRCA1/2 genes." (PMID 29731958, 2018). "According to the US National Cancer Institute, specific inherited mutations in BRCA1 and BRCA2 increase the risk of female breast and ovarian cancers, “and they have been associated with increased risks of several additional types of cancer." (PMID 29445722, 2018). "In addition, a dominantly inherited 5′ UTR BRCA1 variant was recently shown to be associated with BRCA1 promoter hypermethylation, which is known to impact TF binding, and associated allelic loss of BRCA1 expression in two families affected by breast and ovarian cancers." (PMID 30204945, 2018). "For the BRCA1 gene, it was detected in about 3%and 11% of breast and ovarian carcinomas, respectively." (PMID 30453575, 2018). "For carriers of the high-penetrance cancer-susceptibility genes BRCA1 and BRCA2, the life-time risk of ovarian cancer, and particularly high-grade serous carcinoma, is between 40–70 and 20–50%, respectively." (PMID 29464354, 2018). "Gene predisposition, such as BRCA1 and BRCA2 mutation, also contributes significantly to ovarian cancer." (PMID 30061175, 2018). "Among the ovarian cancer patients, BRCA mutations were identified in 8.39% (13/155) of the patients, including 9 BRCA1 and 4 BRCA2." (PMID 29487695, 2018). "Nonetheless, bilateral salpingo-oophorectomy by age 35 for BRCA1 mutation carriers and 45 for BRCA2 mutation is strongly recommended to prevent ovarian cancer, and has also been shown to impact on survival." (PMID 30572612, 2018). "As a result, unique fluorescence emission with excellent stability was observed in DNA-Ag NCs in choline dhp, and a turn-on fluorescence-sensing platform was built for the detection of the BRCA1 gene, which is related to familial breast and ovarian cancers." (PMID 30404141, 2018).